H19 (H19 imprinted maternally expressed transcript)
Diseases named in the same sentence as H19 in open-access papers (continued):
Sharing a sentence is not in itself a finding about the gene and the disease.
tumor (continued). "Additionally, stromal CAF-derived H19 can be transferred to cancer cells, further contributing to the spread and progression of chemoresistance within the tumor." (PMID 40781643, 2025). "For example, restoring the miR-200c family, which is downregulated in TNBC, or targeting the oncogenic lncRNA H19 may offer novel pathways to inhibit tumor progression." (PMID 41378290, 2025). "Furthermore, we investigated the influence of lncRNA H19 on tumor development using an in vivo xenograft tumor model." (PMID 40297808, 2025). "Additionally, multiple studies have found that lncRNA H19 is overexpressed in gastrointestinal tumors, participating in tumor development and chemotherapy resistance by regulating abnormal gene expression." (PMID 40861273, 2025). "H19 (imprinted maternally expressed transcript) functions as an oncogene and is overexpressed in HNSCC, being associated with higher invasive capacity of tumor cells and worse overall survival." (PMID 41020820, 2025). "RT-qPCR analysis confirmed efficient overexpression of H19 in the tumor tissues." (PMID 41208889, 2025). "Moreover, lncRNAs such as H19 and MALAT1 have been implicated in resistance to anti-VEGF therapies, facilitating angiogenesis and tumor microenvironment remodeling." (PMID 40781643, 2025). "In the past, research on H19 mainly focused on its role in tumor cell proliferation." (PMID 40076761, 2025). "Compared to normal tissues, tumor tissues had considerably lower H19 levels." (PMID 41208889, 2025). "H19 may influence the expression of tumor-suppressive miRNAs and drug efflux transporters, resulting in drug resistance and decreased intracellular concentrations of chemotherapeutic agents." (PMID 40142329, 2025). "High expression of lncRNA H19 was also observed in GBM tumor tissues according to TCGA-LIHC data." (PMID 40297808, 2025). "By assessing autophagy flux levels, the study of metformin found that its powerful tumor-inhibiting ability may be thwarted by down-regulating H19-mediated ROS production to inhibit autophagy, thus impeding cancer cell vitality." (PMID 40028033, 2025). "Also, H19 promotes the tumor’s sensitivity to DAs by functioning as a sponge for miR-93, inhibiting its expression and increasing the expression of ATG7, a protein involved in autophagy." (PMID 40362297, 2025). "Research indicates that low concentrations of butyrate may promote tumor progression and metastasis by upregulating H19 expression and facilitating M2 macrophage polarization and function." (PMID 41416095, 2025). "For clinical translation, CICRlncRNAs could be detected in liquid biopsies (e.g., plasma exosomal RNA via RT–qPCR) or tumor tissues (via RNA in situ hybridization), similar to established lncRNA biomarkers such as H19 in GC." (PMID 40697378, 2025). "Furthermore, H19 influences angiogenesis, apoptosis, cell proliferation, and metastasis, among other aspects of tumor biology." (PMID 41208889, 2025). "Furthermore, H19 can be secreted into exosomes, which has been reported to promote the chemoresistance of tumor cells against oxaliplatin and doxorubicin, both in vivo and in vitro." (PMID 40429961, 2025). "Additionally, H19 was also shown to induce tumor-specific pyruvate kinase M2 (PKM2), which is pivotal for the Warburg effect and tumor angiogenesis." (PMID 39403602, 2024). "Furthermore, lncRNA H19 has been found associated with the regulation of TGF-β/SMAD3 in HCC, impacting tumor growth." (PMID 38279330, 2024). "Deliberate manipulation of H19 expression levels within tumor cells could also serve as a means to modulate their aggressive behavior." (PMID 38166752, 2024). "Furthermore, when serum exosomal H19 levels were compared between BC patients before and 7 days after surgical removal of the tumor mass, H19 levels were significantly lower in postoperative patients than in preoperative patients." (PMID 39148900, 2024). "Previous studies have found that H19 is a tumor-promoting factor in HCC cells." (PMID 38334963, 2024).
tumor (continued). "By activating the Wnt/β-catenin pathway, H19 suppresses apoptosis in tumor cells." (PMID 38355574, 2024). "H19 acts as an endogenous sponge for the tumor suppressor let-7 to regulate cancer metastasis." (PMID 39170516, 2024). "In line with this, it has been reported that H19 is a downregulated lncRNA in prolactinoma tissues; H19 ectopic expression decreases cell proliferation in vitro and tumor growth in vivo; the increased expression of H19 has been superior to the anti-tumoral effect of cabergoline." (PMID 39702128, 2024). "Also, combined cabergoline treatment with H19 decreases tumor growth in vivo; however, miR-93a mimics significantly increase prolactinoma growth in vivo." (PMID 39702128, 2024). "H19 is known to have dual roles, functioning both as an oncogenic and tumor suppressor." (PMID 39659621, 2024). "Furthermore, heightened expression of H19 in CAFs escalates lactate secretion, fostering a highly acidic tumor microenvironment that is propitious for tumorigenesis." (PMID 39717771, 2024). "Also, tumor-supporting cells, like cancer-associated fibroblasts, release EVs containing Annexin A6, miR-21, or lncRNA H19, which contributes to the development of stem-like properties and resistance to chemotherapy in tumor cells." (PMID 38796692, 2024). "Both alpha-fetoprotein and H19 expression are potent tumour markers in adult liver tissue." (PMID 38992336, 2024). "Consequently, the expression level of H19 serves as a biomarker for cancer diagnosis, prognosis evaluation, and monitoring treatment response in the tumor microenvironment." (PMID 39286016, 2024). "Additionally, H19 can promote tumor cell growth, invasion, and migration through the H19/miR-200a/CDK6/ZEB1 axis." (PMID 38715092, 2024). "Previous studies found the function of H19 in multiple tumor types, but H19 expression in GC and its clinical significance remain unclear." (PMID 39184399, 2024). "Studies indicate that the knockdown of lncRNA H19 inhibits tumor formation in vivo." (PMID 38791310, 2024). "H19 may act as a tumor suppressor, keeping cells from growing and dividing too quicklyor in an uncontrolled way." (PMID 38791310, 2024). "H19 may also interact with other non-coding RNAs, proteins, or metabolites, maintaining the homeostasis of the tumor microenvironment." (PMID 39286016, 2024). "Interestingly, the levels of H19 in the blood were observed to decrease following surgical excision of the tumor." (PMID 38166752, 2024). "However, IMPs, particularly IGF2BPs, appear to resume their physiological functions in tumour cells and exhibit multiple attachments to H19 lncRNA69." (PMID 38616192, 2024). "H19 also promotes tumor growth by recruiting and binding to eIF4A3." (PMID 38355574, 2024). "High tumor expressions of H19 were associated with the size of the tumor, nodal status and hormone negativity, having a negative correlation with the prognosis of BC." (PMID 36831100, 2023). "Moreover, treatment with CSCs-EVs increased tumor weight of mice, while CSCs-EVs-sh-H19 reduced the weight." (PMID 37005676, 2023). "For example, lncRNA H19 has been considered as an oncogene in a variety of tumor cells." (PMID 37904679, 2023). "H19 RNA is a novel biomarker for the diagnosis and monitoring of neoplasms." (PMID 37189829, 2023). "Additionally, H19 acts as a molecular sponge to sequester let-7, a miRNA family that acts as a tumor suppressor in EOC." (PMID 38004379, 2023). "Tumor volumes were different in overexpression H19, knockdown H19, and control." (PMID 37821504, 2023). "Furthermore, several in vitro and in vivo studies demonstrated that the overexpression of H19 significantly reduced tumor growth." (PMID 37958474, 2023). "Our previous study showed that knockdown of lncRNA H19 expression could enhance the anti‐tumour effect of natural products." (PMID 37307404, 2023).
tumor (continued). "Furthermore, the expression of oncogenic LncRNA H19, which is constitutively expressed in various tumor types like breast cancer, was significantly down-regulated due to the treatment of MDA-MB-231 cells with IDET." (PMID 36770654, 2023). "In CRC, H19 may facilitate interactions with immune cells within the tumor stroma, thereby influencing disease progression." (PMID 37760852, 2023). "Due to the variable expression of H19 in different types of tumours, its role as a tumour marker was speculated." (PMID 37189829, 2023). "In the presentstudy, we found that the level of H19 expression increases in ALL patientsthat might have a tumor promoter in ALL, which is in harmony with other studies." (PMID 36680478, 2023). "In conclusion, our data expand the knowledge of endocan biology in NSCLC, showing that this PG can regulate the expression of tumor-related genes, including epigenetic regulators such as lncRNAs H19 and HULC; furthermore, it promotes tumor cell migration and proliferation." (PMID 37175885, 2023). "Moreover, another study has found that the overexpression of H19 brought about a reversal in the tumor inhibitory effects of Huaier extract, yet its knocking down sensitized BC cells to Huaier extract." (PMID 36831100, 2023). "Additionally, the positive expression of nuclear YAP and CDX2 proteins was robustly induced in tumor tissues of CSCs-EVs-treated mice while an opposite effect was identified in the presence of sh-H19." (PMID 37005676, 2023). "Moreover, high H19 expression was significantly correlated with tumor size, advanced tumor node metastasis (TNM) stage, and postoperative recurrence of CCA." (PMID 36960964, 2023). "Moreover, very recently, a study highlighted a novel TGF-β and H19 (known to bind CTCF) signaling axis in tumor-initiating hepatocytes that importantly regulates hepatic carcinogenesis." (PMID 37414929, 2023). "LncRNA-MEG3 mostly acts as a tumor suppressor, in contrast to H19." (PMID 37635248, 2023). "After ensuring that measured H19 derived only from inside EVs, the authors observed that H19 levels were increased in BC patients compared to HC and benign disease, further correlating with tumor stage." (PMID 37047731, 2023). "H19 imprinted maternally expressed transcript is located at chromosome 11p15.5 near the insulin-like growth factor 2 (IGF2) gene and encodes an approximately 2.3-kb lncRNA located in the cytoplasm that can act as a tumor-suppressor or oncogene." (PMID 36362925, 2022). "Moreover, overexpression of H19 enhances the ability of tumor cells to invade in vitro and metastasize in vivo." (PMID 35103065, 2022). "In addition, the existence of H19 in exosomes involved in tumor progression promotes its significance in this pathology because it is supposed to be a predictor marker for breast, stomach, and lung malignancies and a prognostic marker." (PMID 36671388, 2022). "In addition to its oncogenic function in tumor formation, a high level of H19 in tumor tissues has also been reported to be an indicator for poor prognosis." (PMID 36090894, 2022). "siRNA-mediated downregulation of H19 or UHMK1 inhibited tumor proliferation and xenograft growth." (PMID 35359403, 2022). "Methylation of the H19 promoter in EBV-positive tumor cell lines." (PMID 35674441, 2022). "Moreover, Immune infiltration analysis revealed that each component in the ceRNA network (H19/miR-378a-5p/SERPINH1) was significantly correlated with the infiltration abundances of diverse tumor-infiltrating immune cells." (PMID 36104825, 2022). "However, reexpression of H19 was observed in several different tumors; therefore, H19 RNA has been proposed as a marker of embryonal dedifferentiation of adult tissues and as a tumor marker." (PMID 35796900, 2022). "Moreover, the function of H19 in hematologic tumors is seemingly much more complex than that in other tumor types because of the highly heterogeneous pathogenesis." (PMID 36588790, 2022).
tumor (continued). "H19 is a maternally expressed imprinted gene, and its transcription gives rise to a fetal lncRNA that also functions as a precursor to microRNA miR675, which negatively affects cell proliferation and tumor metastasis." (PMID 36231092, 2022). "As the summary of potential mechanisms associated with H19 and different anti-tumor drugs, three common ways to promote MDR through H19 are proposed: gene methylation and nuclear epigenetic changes, miRNA control in cytoplasm, and direct association with certain protein/transcription factors (TFs)." (PMID 36246634, 2022). "Interestingly, both Erlotinib-resistant tumor from different patients and Erlotinib-resistant cell lines display low H19 expression levels." (PMID 35955440, 2022). "Given the multiple mechanisms of action known for lncRNAs, it is not surprising that the same lncRNAs may exert dual functions in cancer, acting as either tumor suppressors or oncogenes, depending on the cancer type (H19, BANCR, TINCR, MALAT, XIST)." (PMID 35159386, 2022). "Moreover, m5C can modify the lncRNA, H19, to recruit oncoproteins and promote tumor proliferation and invasion." (PMID 35692827, 2022). "However, it is found that H19 also shows a tumor suppressor function in teratocarcinomas and pituitary tumors." (PMID 36246634, 2022). "Further study demonstrates that H19 displays a cell-dependent and/or tumor type-dependent function." (PMID 36246634, 2022). "Furthermore, downregulation of H19 in TNBC is translated into lower tumor growth rate in vivo and reduced cell proliferation accompanied by higher rates of apoptosis." (PMID 35955440, 2022). "H19 alterations occur in the early stages of cancer development and are thought to be involved in protein translational dysregulation and genomic instability, leading to cell proliferation imbalance and tumor metastasis." (PMID 36139647, 2022). "H19 is involved in the regulation of cell proliferation (vascular endothelial or tumor) through the negative regulation of miR152 to involve angiogenesis or tumor pathogenesis." (PMID 35345660, 2022). "Therefore, through negative regulation of miR-140-5p, H19 stimulates the tumor-promoting activity of FGF9 in SCLC." (PMID 36188624, 2022). "Its silencing by the lncRNA H19 is positively correlated with LSCC progression through DNMT1 activation and subsequent hypermethylation of downstream suppressor genes, and significantly associated with tumor grade, differentiation, LNM, and clinical stage." (PMID 35406495, 2022). "Several pieces of evidence suggest that H19 exerts oncogenic and tumor suppressor activities." (PMID 35456025, 2022). "Finally, we established the xenograft model to demonstrate the effect of TAMs-exo-derived H19 on tumor progression and autophagy in vivo." (PMID 35607322, 2022). "Additionally, H19 expression was downregulated in human PA tissues and was negatively correlated with disease progression, while the upregulation of H19 inhibited tumor growth and cell proliferation." (PMID 36139495, 2022). "Additionally, H19 diminished the inhibitory effect of miR-181d on β-catenin by sponging this tumor suppressor miRNA." (PMID 34322395, 2021). "The experimental study showed that an up-regulation process of LncRNA H19 was observed in cancer cell lines compared with the non-cancerous cell lines, which associated with an elevated invasive behavior in tumor cell." (PMID 33799753, 2021). "This study suggests that chrysin exhibited anti-tumor effects through a H19/let-7a/COPB2 axis." (PMID 34150620, 2021). "Moreover, the EGFR wild-type LADC subject with LncRNA H19 SNP rs217727 or rs2107425 was correlated to severe tumor grade, especially higher tumor T status." (PMID 33799753, 2021). "H19 has both tumor-promoter and tumor-suppressive functions." (PMID 34069428, 2021). "We speculate that this could be due to the reduced number of tumor cells that express H19 and miR-675 or due to as yet unknown mechanisms that abrogate the degradation of FADD mRNA by miR-675." (PMID 33499244, 2021).
tumor (continued). "Some studies showed that LncRNA H19 could participate in the regulation of various biological processes such as cell proliferation, apoptosis, and metabolism; others also indicated that lncRNA H19 regulated tumor carcinogenesis, angiogenesis, and metastasis." (PMID 33716779, 2021). "siRNA-mediated inhibition of H19 or APOBEC3G mimicked the tumor-inhibiting effect of sulforaphane." (PMID 33669381, 2021). "Studies on the expression, recruitment of chromatin trimmings, regulation of X chromosome inactivation (XIST), genomic imprinting (H19), protein folding and protein activity, other processes have revealed that lncRNAs can function carcinogenic or tumor suppressor genes in tumor development." (PMID 33522895, 2021). "About its primary function, the LncRNA H19 exists in heart, skeletal muscle and breast and can modulate the cell proliferation, cell differentiation and the oncogenic effects for development of neoplasms." (PMID 33799753, 2021). "Some reported that H19 is a tumor suppressor and others that it has oncogenic properties." (PMID 33499244, 2021). "H19 expression was markedly elevated in 3 of the 4 NEPC organoids compared to organoids derived from normal prostate or PCa patients who underwent primary tumor resection for AdPC." (PMID 34934057, 2021). "Furthermore, the LncRNA H19 SNP rs217727 and rs2107425, especially the LncRNA H19 SNP rs217727, are correlated to an advanced tumor status for LADC individuals with EGFR wild-type." (PMID 33799753, 2021). "To further examine the effect of lncRNA H19 on tumor progression and the PFKFB3 gene-mediated glycolysis pathway in vivo, we established a nude mouse transplanted tumor model and used shRNAH19-1720 (named sh-H19) to knockdown the expression of lncRNA H19 in oral CAFs." (PMID 33762576, 2021). "H19 is a developpmentally regulated gene with putative tumor suppressor activity." (PMID 33658067, 2021). "However, the degree of methylation gain at H19 in Subgroup B tumours is higher than in Subgroup A. This implies that—along with other epigenetic changes—he clones containing this alteration become more dominant in this subgroup." (PMID 33012783, 2021). "Taken together, these studies indicate that H19 is closely related to the occurrence and development of tumours; however, its role may differ in different types of cancer." (PMID 33236528, 2021). "Furthermore, subcutaneous injection of organoids with H19 knockdown (OWCM-155-shH19) in mice demonstrated significantly slower growth with reduced tumor weight and volume as compared to mice injected with control (OWCM-155-shSCR) organoids." (PMID 34934057, 2021). "In CCRCC, the overexpression of lncRNA H19 was proved to promote the carcinogenesis of tumor." (PMID 34598322, 2021). "Furthermore, our in vivo tumor metastasis study results revealed that lncRNA H19 knockdown in oral CAFs increased E-cadherin in transplanted tumors." (PMID 33762576, 2021). "Downregulation of H19 has been correlated with tumor progression." (PMID 34885097, 2021). "Furthermore, H19 was shown to be essential for tumor metastasis and was found to be involved throughout the process of tumorigenesis." (PMID 35011635, 2021). "Since then, numerous studies demonstrated the different mechanisms through which H19 contributes to tumorigenesis or may act as a tumor-suppressive lncRNA." (PMID 32331331, 2020). "Furthermore, exosomal H19 disseminates gefitinib resistance by targeting gefitinib-sensitive tumor cells." (PMID 33072553, 2020). "Notably, tumor lymph angiogenesis was also significantly repressed after lncRNA H19 or TNFAIP8 knockdown." (PMID 32514245, 2020). "Data from in vivo models point towards a tumor suppressor effect of H19 in HCC." (PMID 32429417, 2020). ", 2018), the combination of pan‐PIM kinase inhibitors with concomitant H19 KD reduces tumor growth." (PMID 32146726, 2020).